FAAH (fatty acid amide hydrolase)
Diseases named in the same sentence as FAAH in open-access papers (continued):
Sharing a sentence is not in itself a finding about the gene and the disease.
Anxiety (continued). "For example, administration of the viral mimetic poly I:C produces changes in thermoregulation, pain sensitivity and anxiety, which are reversed by administration of a FAAH inhibitor." (PMID 33452437, 2021). "In this review, we excluded publications assessing anxiety-like behavior in order to assess the function of FAAH in isolated cases of depression." (PMID 33494322, 2021). "We administered a FAAH inhibitor (PF) acutely at two doses and examined anxiety-like behavior in the EPM in order to investigate the relevance of changes in eCB levels to the increase in anxiety-like behavior." (PMID 33452437, 2021). "More so, FAAH also metabolizes oleoylethanolamide (OEA) and palmitoylethanolamide (PEA) which have also been implicated in anxiety and inflammation." (PMID 33452437, 2021). "This is in contrast to the published literature which demonstrated that acute FAAH inhibition reduced anxiety-like behaviour in the EPM and increased stress coping behaviour in the FST in VPA-exposed male adolescent rats." (PMID 34207178, 2021). "Colitis-induced anxiety was reversed following acute central inhibition of FAAH, suggesting that the reductions in AEA produced by colitis contributed to the generation of anxiety." (PMID 33452437, 2021). "Inhibition of FAAH has been considered as a treatment option for anxiety and other psychological disorders; however, a clinical trial of one compound in 2016 caused severe adverse effects including one death." (PMID 32595741, 2020). "In conclusion, the present study demonstrates that kaempferol has the potential of facilitating extinction of aversive memories along with alleviation of anxiety possibly through eCB augmentation via inhibition of the FAAH enzyme." (PMID 33066366, 2020). "NAT is decomposed by FAAH into taurine, whose role in the pathophysiology of anxiety is quite controversial." (PMID 32116530, 2020). "URB597 (0.3 mg/kg), an FAAH inhibitor, proved to reduce anxiety in a CB1-dependent manner in a rodent model." (PMID 32316328, 2020). "Counterintuitively, FAAH overexpression in basolateral complex of amygdala (BLA) reduced anxiety-like behaviors." (PMID 32316328, 2020). "Mimicking anandamide reduction by selectively overexpressing FAAH at hippocampal CA3-CA1 synapses led to increased anxiety along with an enhancement of LTP expression in vitro, while i-LTD and DSI remained unchanged." (PMID 32848597, 2020). "Genetic as well as pharmacologic approaches strongly support the idea that FAAH knockout mice and the wild-type administered with FAAH inhibitor (URB597) showed reduced anxiety-like behavior upon exposure to light-dark and elevated plus-maze (EPM) tests." (PMID 33066366, 2020). "Conversely, our data show that genetically-induced FAAH overexpression in hippocampal pyramidal neurons elicited anxiety-like behavior." (PMID 30532004, 2019). "Stress exposure can cause a decrease in AEA levels, through mobilization of FAAH, and an increase in 2-AG levels, in brain regions such as amygdalar and prefrontal cortical areas, which are critical for the expression of anxiety and fear-related behaviors." (PMID 31561480, 2019). "It appears that aversively motivated learning is most sensitive to be enhanced by FAAH manipulations, possibly due to the effects of FAAH inhibition on anxiety-related responses or coping behavior." (PMID 31004320, 2019). "Genetic deletion and pharmacological inhibition of FAAH reduce anxiety and improve emotional responses and memory in rodents and humans." (PMID 30532004, 2019). "Nevertheless, because FAAH activity appears to be increased by chronic restraint stress in animal models as well as by anxiety-like behaviors, FAAH inhibition by CBD appears to us as a possible alternative to explain the CBD effects in aversive memories." (PMID 30087591, 2018).
Anxiety (continued). "In mouse models for anxiety or pain, pharmacological or genetic blockade of eCB degrading enzymes such as FAAH or MAGL led to increased levels of AEA and 2-AG, respectively, which finally resulted in analgesic and anxiolytic effects." (PMID 29849009, 2018). "FAAH inhibition has been shown to exert rapid and long-lasting anti-anxiety effects in behavioral paradigms such as acute inescapable stress or chronic corticosterone administration, but the specific mechanisms are still not well understood." (PMID 30687006, 2018). "This suggests that the effects of FAAH inhibition on anxiety-like behavior depend on the strain of mice, as well as testing environment." (PMID 29695817, 2018). "To examine the effects of FAAH, MAGL or dual FAAH/MAGL inhibitors in the regulation of anxiety, we tested the FAAH inhibitor PF-3845 (1 mg kg–1), MAGL inhibitor JZL184 (10 mg kg–1) or dual FAAH/MAGL inhibitor JZL195 (10 mg kg–1) in the light–dark box assay." (PMID 29695817, 2018). "In agreement, the pharmacological blockade of FAAH was shown to reduce anxiety in a variety of animal models, such as the elevated plus maze and light–dark box test, and these effects were enhanced under aversive stimuli." (PMID 30279403, 2018). "Inhibitor of FAAH induces antidepressant-like effects in rodents and genetic deletion of FAAH in mice confers resistance to anxiety-like and depression-like behavioral responses." (PMID 28680401, 2017). "A link between the anxiety-related effects of FAAH inhibitors and their ability to enhance endogenous AEA signalling has been already proposed." (PMID 26360704, 2015). "ST4070 clearly inhibited FAAH activity and augmented the levels of two of its substrates, N-arachidonoylethanolamine (anandamide) and N-palmitoylethanolamine, in anxiety-relevant brain regions." (PMID 26360704, 2015). "Nevertheless, we believe that these findings represent an important first step towards an understanding of the potential anxiolytic-like and cardioprotective properties of FAAH inhibitors in preclinical models of anxiety." (PMID 26656183, 2015). "A second candidate is the type 1 cannabinoid (CB1) receptor that renders food more or less pleasurable and mediates the reduction of anxiety-like behaviour induced by the inhibition of the endocannabinoid-degrading enzyme fatty acid amide hydrolase (FAAH)." (PMID 24482678, 2014). "Within the PFC, overexpression of FAAH reduces AEA levels and increases anxiety, while infusion of low doses of a FAAH inhibitor into the PFC reduces anxiety measures in the elevated plus-maze." (PMID 24286185, 2013). "Unequivocally, the effects of pharmacological FAAH inhibition or genetic deletion are blocked by CB1 receptor antagonists, indicating that FAAH inhibition reduces anxiety through augmentation of AEA signaling at the CB1 receptor." (PMID 24286185, 2013). "FAAH inhibition also decreases anxiety in the rat pup ultrasonic vocalization test, light–dark exploration assay and marble-burying assay." (PMID 24286185, 2013). "In this regard, it is interesting to note that inhibitors of fatty acid amide hydrolase have been proposed to reduce the symptoms of anxiety and depression." (PMID 22373123, 2012). "Currently, the most promising candidates are inhibitors of endocannabinoid catabolic enzymes (e.g., anandamide, FAAH) for the treatment of anxiety and depressive disorders." (PMID 24281562, 2012). "In accordance with this finding, a number of previous studies have shown that inhibition of fatty acid amide hydrolase, the enzyme responsible for degradation of anandamide, induces anxiolytic-like effects in different animal models of anxiety." (PMID 23493622, 2012). "On the other hand, inhibition of FAAH by URB597, leading to further increase in AEA mediated neurotransmission results in a reversal of anxiety-like responses associated to nicotine withdrawal." (PMID 22140525, 2011).
Anxiety (continued). "Indeed, diet abstinence evokes changes in both anxiety- and depression-related behaviors, which are significantly ameliorated by the administration of FAAH inhibitor PF-3845." (PMID 39582223, 2025). "Targeting this axis and modulating it with eCBome enzyme/receptor (such as FAAH/TRPV1) blockers may have therapeutic potential in ASD-related anxiety and depressive tendencies as well as behavioral and sociability impairment." (PMID 40605060, 2025). "We can suppose that URB 597, by inhibiting FAAH and increasing AEA levels, activated CB1 receptors, which are mostly implicated in the regulation of fear and anxiety responses, especially those located in brain regions like the hippocampus, amygdala and prefrontal cortex." (PMID 40005177, 2025). "Anxiety and depression often involve an overexpression of FAAH in the amygdala and hippocampus." (PMID 40605060, 2025). "Indeed, in animal models of ASD, FAAH inhibitor improved aversion memory and relieved anxiety behavior and depression, reversed social impairment, communication deficits, stereotyped behavior, and repetitive and atypical emotion-related behaviors." (PMID 40605060, 2025). "Consequently, it is reasonable to consider the downward trend in FAAH mRNA expression levels 5 h after drug administration as negatively influencing mobility and anxiety-like behaviors in the long term." (PMID 38542057, 2024). "Indeed, FAAH inhibitors not only ameliorated stress-induced anxiety but also promoted the extinction of aversive memories in several paradigms." (PMID 37958761, 2023). "Given that FAAH is a potential target for the treatment of pain, anxiety, depression and other neurological disorders, this new understanding of the regulatory role of the FAAH-OUT gene provides a platform for the development of future gene and small molecule therapies." (PMID 37222214, 2023). "However, this seems to be of little importance in the case of anxiety, as the consequences of FAAH and MAGL inhibition appear similar, even though differences were observed in other behaviors." (PMID 37958761, 2023). "As such, these short-term pharmacological studies in humans generally support the previous literature and suggest that there may be some therapeutic potential for FAAH inhibition for the management of anxiety and stress-related psychiatric disorders." (PMID 37671673, 2023). "The protein FAAH is activated during stress exposure circumstances, which raises the neuronal excitability in the amygdala, a critical brain area that mediates anxiety." (PMID 37372343, 2023). "In humans, carriers of the FAAH 385A allele, which results in destabilised FAAH proteins and elevated anandamide levels, have been found to self-report lower anxiety compared to non-carriers." (PMID 37085531, 2023). "We showed earlier that aversive testing conditions enhanced the effects of CB1 gene disruption on anxiety and hypothesized that the same was true for FAAH inhibition." (PMID 37958761, 2023). "FAAH inhibitors may also be useful in conditions involving chronic pain (e.g., cancer, fibromyalgia) stress, and anxiety." (PMID 37958761, 2023). "In contrast, inhibiting FAAH reduces anxiety-like behaviour and may provide an antidepressant effect by stimulating the CB1 receptor." (PMID 37895295, 2023). "Nevertheless, it was observed that FAAH inhibition prevented this anxiety-like behavior." (PMID 36829752, 2023). "Furthermore, the chemical inactivation of FAAH leads to an increase in neuronal transmission and/or counter controls to neuroinflammation and pain, including depression and anxiety." (PMID 35159280, 2022). "The same FAAH polymorphism (rs324420), combined with the minor allele combination of rs7209436C, rs110402, and rs242924G of the CNR1 gene, was associated with an increased risk of developing anxiety." (PMID 35563156, 2022).
Anxiety (continued). "Low FAAH activity and high AEA concentrations are associated with the A allele of the C385A polymorphism, which showed higher frequency in individuals with increased anxiety and depression scores." (PMID 35563156, 2022). "In opposition, the inhibition of FAAH decreases anxiety-like behavior and may produce an antidepressant effect mediated by CB1 receptor stimulation." (PMID 36101457, 2022). "Indeed, clinical studies reported that genetic polymorphisms that decrease FAAH activity and increase baseline AEA levels are associated with reduced anxiety." (PMID 35159280, 2022). "In support of this hypothesis, Morena, Hill, and colleagues have provided evidence in rats that high FAAH activity in the amygdala is associated with low AEA concentrations and reduced HPA axis activation, anxiety, and expression of conditioned fear." (PMID 35105857, 2022). "By contrast, dampened AEA-CB1R circuitry through increased FAAH expression may contribute to increased levels of neuroticism, including trait anxiety and depression, which was observed in our sample of ASPD and BPD participants." (PMID 35064143, 2022). "DAGLα, NAPE-PLD and FAAH expression were also reduced in the prefrontal cortex and hippocampus in S1 mice, brain areas which are also important mediators of fear regulation and anxiety." (PMID 36081934, 2022). "FAAH gene polymorphism appears to correlate with higher baseline cortisol levels but not anxiety in this study." (PMID 35563156, 2022). "Thus, the effect of enhancing AEA and 2-AG tone following FAAH or MGL inhibition on anxiety-like behavioural responding in VPA-exposed female rats was examined." (PMID 34207178, 2021). "Acute FAAH inhibition reverses social impairments, cognitive deficits, repetitive- and anxiety-like behaviours and increases stress coping behaviours in VPA-exposed male adolescent rats, while acute MGL inhibition rescues social deficits and repetitive-like behaviours." (PMID 34207178, 2021). "For example, recently completed trials have found a positive signal for the FAAH inhibitor JNJ-42165279 in reducing anxiety symptoms in patients with social anxiety disorder and the FAAH inhibitor PF-04457845 in reducing cannabis withdrawal in men with cannabis dependence." (PMID 34959715, 2021). "This suggests that inhibition of FAAH by JNJ-42165279 could influence trait anxiety more than state anxiety." (PMID 33070154, 2021). "Based on the outcomes of the initial experiments in this study, we made the a priori hypothesis that colitis would increase anxiety-like behavior and that treatment with a FAAH inhibitor would reverse that." (PMID 33452437, 2021). "As such, this would suggest that inhibition of FAAH could represent a novel therapeutic approach to managing comorbid anxiety in peripheral inflammatory diseases." (PMID 33452437, 2021). "Our computational study showed that Kaempferol interacted with the catalytic amino acids (SER241, PHE192, PHE381, and THR377) of FAAH enzyme Conclusion: Our study demonstrate that kaempferol facilitated the extinction of aversive memories along with a reduction of anxiety." (PMID 33066366, 2020). "Inhibition of FAAH through gene deletion or pharmacological inhibition can interfere with stress-induced reductions in AEA and the associated anxiety- and learned fear-like behaviors, an effect mediated through AEA-CB1 receptor interactions in amygdalar brain regions." (PMID 31561480, 2019). "This suggests an increase in anxiety-like behavior in FAAH-overexpressing mice." (PMID 30532004, 2019). "This suggests that dual FAAH/MAGL inhibition might increase anxiety-like behavior under basal conditions depending on experimental context." (PMID 29695817, 2018). "Thus far, only FAAH inhibition has been explored to address post-traumatic anxiety, and was found to protect against TBI-induced increases in anxiety-like behavior in mice." (PMID 28261100, 2017).
Anxiety (continued). "Furthermore, recent evidence has shown that CRF1 activation in the amygdala induces FAAH and reduces AEA levels, an effect associated with anxiety-related behavior." (PMID 26342110, 2015). "Taken together, these findings prompt further investigation aimed at determining whether inhibition of FAAH activity may represent a viable pharmacological strategy for the treatment of the comorbidity of cardiovascular disease with anxiety and mood disorders." (PMID 26656183, 2015). "Furthermore, both pharmacological and genetic inhibition of FAAH prevents chronic restraint stress-induced anxiety in the elevated plus-maze, as well as CUS-induced anhedonia." (PMID 24286185, 2013). "Blocking FAAH-mediated AEA degradation decreases anxiety in the elevated plus-maze, and the light–dark box test; importantly, several studies indicate these effects are enhanced under conditions of high environmental aversiveness or following exposure to stress." (PMID 24286185, 2013). "Similarly, administration of a CB1 receptor antagonist into the basolateral nucleus of the amygdala (BLA) increases anxiety, while inhibition of FAAH in the BLA reduces anxiety." (PMID 24286185, 2013). "Similarly, FAAH-/- mice exhibit reduced anxiety in the light–dark box assay and elevated plus-maze during conditions of high aversiveness, but not low stress conditions." (PMID 24286185, 2013). "Furthermore, recent work characterised a mutation in the human FAAH chromosomal region in a patient with lifelong insensitivity to pain and lack of anxiety." (PMID 39855935, 2025). "Importantly, URB937 administration after TMT exposure partially (1 mg/kg) or completely (3 mg/kg) abolished these behavioral effects, suggesting that post-stress inhibition of peripheral FAAH activity prevents the development of anxiety-like behaviors in male rats exposed to TMT." (PMID 37932554, 2025). "Due to the influence of rs324420 on FAAH activity and endocannabinoid tone, this polymorphism is considered a potential modifier of the response to pharmacological interventions targeting the ECS (e.g., FAAH inhibitors) and as a risk/stratification marker in studies on AUD and anxiety." (PMID 41465160, 2025). "Enhancement of peripheral FAAH-regulated lipid signaling prevents the emergence of stress-induced social avoidance and anxiety-like behaviors in male rats through mechanisms that may involve an attenuation of peripheral cytokine release induced by stress exposure." (PMID 37932554, 2025). "Moreover, it is tempting to speculate that the ELS-induced downregulation of FAAH expression in the mPFC, observed in the ELS-exposed males, may be associated with the measured symptoms of reduced anxiety." (PMID 39503008, 2024). "Similarly, reducing the anandamide level in the BLA by overexpression of fatty acid amide hydrolase led to reduced anxiety-like behavior in male rats via a GABAA receptor-dependent mechanism, supporting an endocannabinoid modulatory role at inhibitory synapses in anxiety-like behaviors." (PMID 38994327, 2024). "For instance, the Fatty Acid Amide Hydrolase (FAAH) rs324420 is a polymorphism thought to play roles in neural functions and has been previously found to be associated with athletic performance in shaping anxiety-like behavior and affecting leadership and persistence." (PMID 36101457, 2022). "FAAH inhibition is considered a powerful approach to enhance the endocannabinoid signalling, and therefore it has been largely studied as a potential target for the treatment of neurological disorders such as anxiety or depression, or of inflammatory processes." (PMID 30688118, 2019). "Oleoylethanolamide and other cannabinoid-like compounds have been proposed for the treatment of anxiety disorders and one of the mechanisms by which this compound could have a beneficial impact on anxiety could be slowing down of AEA degradation by competing with it for FAAH activity." (PMID 30687006, 2018).